MGA (MAX dimerization protein MGA)
Diseases named in the same sentence as MGA in open-access papers (continued):
Sharing a sentence is not in itself a finding about the gene and the disease.
tumor (38 papers, 2007 to 2025). "Lastly, we examined the potentially broader function of MGA as a tumor suppressor by studying the functional consequences of MGA loss in normal and malignant colorectal organoids." (PMID 34236315, 2021). "Here, we demonstrate that MGA loss of function promotes tumorigenesis in vivo and investigate the molecular basis of its tumor suppressive activity." (PMID 34236315, 2021). "Although previous studies have indicated a vital role of MGA in tumorigenesis, the effect of MGA mutations on tumor-host interactions is unclear." (PMID 33927616, 2021). "Longer progression-free survival was found in MGA-mutated patients (HR, 0.41; 95% CI, 0.23–0.73; p = 0.003), and the association remained significant after controlling for tumor mutational burden (TMB), programmed cell death ligand-1 expression, and treatment regimens." (PMID 33927616, 2021). "Somatic loss-of-function mutations of MGA have been observed in solid tumors and may lead to tumor development." (PMID 30514323, 2018). "The second group—MB subtype (MGA mutations and LOH at the BRDT locus)—is characterized by MGA mutations, a tumor suppressor gene, related to MYC overexpression and associated with MAPK, NOTCH3/4 and WNT signaling pathway activation." (PMID 33808787, 2021). "Our work furnishes in vivo evidence for MGA acting as a potent tumor suppressor, identifies genes directly regulated by MGA that are candidates for contributing to oncogenesis and provides model systems for further studies on MGA function." (PMID 34236315, 2021). "Taken together with our observation that MGA stabilizes ncPRC1.6 complex members in tumor cells, our findings strongly implicate MGA as an anchor or scaffold for PRC1.6 even in malignant settings." (PMID 34236315, 2021). "To extend our studies, we aimed to elucidate MGA’s role in other tumor types with a high frequency of MGA alterations." (PMID 34236315, 2021). "EGFR and KRAS genes were classified as oncogenes and STK11, RB1 and MGA genes were classified as tumor suppressors." (PMID 32998690, 2020). "Functioned as a tumor suppressor, MGA gene inhibits MYC-dependent cell growth and malignant transformation through binding with MAX." (PMID 30514323, 2018). "Together, these studies suggest that MGA functions as a tumor suppressor in normal tissues, presumably by antagonizing Myc oncogene or by recruiting PRC1 to target genes." (PMID 30324105, 2018). "A recent study indicated that MGA protein could control the expression of BMPs (Bone Morphogenetic Proteins) gene, whereas BMPs play dual roles in suppressing tumor growth and metastasis and accelerating tumorigenesis." (PMID 41154723, 2025). "Clearly, MYC was the most frequently changed gene across many tumour types, followed by MGA." (PMID 35801728, 2022).
tumor (continued). "The region containing the DUF4801 domain is critical for MGA’s tumor suppressive function." (PMID 34236315, 2021). "Although our data is suggestive of a broad tumor suppressive role of MGA and PRC1.6 via antagonizing transcription of MYC and E2F targets, further studies will be required to elucidate the functional relevance of individual MGA-PRC1.6 targets such as STAG3 in tumorigenesis." (PMID 34236315, 2021). "However, we identified a nonsense mutation in MGA (p.Glu210*), a tumor suppressor gene that interacts with MAX, only in the NB15 relapse tumor." (PMID 28915622, 2017). "Similarly, MGA normally subdues the activity of well-known oncogene MYC; its frequent deletion, truncation, or mutated binding properties across cancers further indicates its role as a tumor suppressor." (PMID 32711844, 2020). "Importantly, ectopic expression of MGA can block Myc-dependent cellular transformation in cell culture assays, implying that it may itself provide a tumor suppressor function in vivo." (PMID 18091988, 2007). "In a small number of cases, these genomic bottleneck events resulted in the derivation of PDX models with a different complement of driver alterations from the same tumor (seen in this study affecting CDKN2A, STK11 and MGA)." (PMID 38821942, 2024). "Recently, three molecular subtypes were proposed, the tumor-suppressor/immune-modulator (TSIM), MGA-BRDT (MB), and HDAC9-EP300-ARID1A (HEA) subtypes, and they are well-correlated with the cell of origin, EBV pattern, genomic alterations, and clinical outcomes." (PMID 35054466, 2022). "Recent studies indicate that MGA function is consistent with it acting as a MYC antagonist and tumor suppressor." (PMID 34236315, 2021). "This is especially important as MGA, via atypical PRC1.6, likely regulates lineage-specific genes to mediate its tumor suppressor role in a context-dependent manner." (PMID 34236315, 2021). "MGA, MAX, E2F6, and L3MBTL2 were seen to bind several thousand promoters in MGA-expressing KP tumor cells suggesting that the PRC1.6 complex plays a broad role in tumor cell gene expression." (PMID 34236315, 2021). "We determined MAX, MGA, MYC, L3MBTL2, E2F6, and RNA polymerase II (RNA pol2, all phosphorylated forms) occupancy in Mga-inactivated and control (empty) KP tumor-derived cells lines." (PMID 34236315, 2021). "Taken together, this data strongly suggests that MGA mediates ncPRC1.6 binding to MYC and E2F targets in human LUAD tumor cells." (PMID 34236315, 2021). "Consistent with mouse Kras tumor data, there appeared to be a significant downregulation of anti-tumor immune responses and decrease in IFN signaling genes such as IFITM1 in MGA-altered cases." (PMID 34236315, 2021). "Frequent loss-of-function mutations were also observed for CD58, IGLL5, IRF1, LTB, MGA and VMP1 in blood cancers, implicating a potential tumour-suppressive role of these genes in the pathogenesis in this tissue type." (PMID 33420369, 2021). "The genes with the most frequent SGMs associated with the three mutational processes are clearly enriched in core TSGs, including early oncogenic drivers such as APC, later drivers of tumor progression and metastasis such as CDH1, as well as less-characterized cancer genes such as EPHA2 and MGA." (PMID 37922356, 2023).
tumor (continued). "Gene set enrichment analysis revealed that several metabolic pathways and a subset of MYC-regulated genes were also upregulated in sgMga tumors, indicating that MGA represses MYC targets, similar to repression by MXDs seen in other tumor models (Yang and Hurlin, 2017)." (PMID 34236315, 2021). "MGA, a transcription factor which interacts with c‐MYC, is a putative tumor suppressor gene." (PMID 33811746, 2021). "Furthermore, MGA expression levels were significantly reduced in ALCL and NK-cell lines as well as in ALCL patients, supporting its tumor suppressor status in these malignancies." (PMID 32922661, 2020). "Furthermore, we found that tumor immunogenicity and antitumor immunity were enhanced in non-squamous NSCLC patients with MGA mutation." (PMID 33927616, 2021). "Our studies establish MGA as a bona fide tumor suppressor in vivo and suggest a tumor suppressive mechanism in adenocarcinomas resulting from widespread transcriptional attenuation of MYC and E2F target genes mediated by MGA-MAX associated with a non-canonical Polycomb complex." (PMID 34236315, 2021). "Therefore overexpression of MGA, caused by (P)RR knockdown, could disturb this balance, limiting the supply of MAX for MYC heterodimerization and antagonizing MYC-dependent cell processes; re-routing the tumour cell from a proliferative to a non-proliferative state." (PMID 35401936, 2022).
cancer (32 papers, 2012 to 2025). A tumor composed of atypical neoplastic, often pleomorphic cells that invade other tissues. "CNVs of the MGA locus (15q15.1) occur in many human cancers, with virtually all cases involving single copy loss." (PMID 35203395, 2022). "We also observed that MGA-mutated cancers harbor significantly higher neoantigen load compared to samples with MGA wild type (p < 0.01)." (PMID 33927616, 2021). "Second, multiple truncating mutations in MGA reported in the pan-cancer TCGA database either remove the DUF region entirely or occur within the DUF region." (PMID 34236315, 2021). "MGA mutations are frequently found in multiple cancer types." (PMID 34617019, 2021). "Phase separation of these proteins would be regulated by kinases, including CDK1, CDK2, and EGFR, and transcription factors, including ZNF407, ZNF318, and MGA proteins, to play functions in cancer." (PMID 41154723, 2025). "MAX gene-associated protein (MGA), a suppressor of MYC, is frequently subject to loss-of-function mutations and copy-number deletions in multiple cancer types." (PMID 35054466, 2022). "MGA, encodes MAX gene-associated protein which is a MYC-interacting transcription factor and antagonizes the transcriptional regulation of MYC involved in cancer processes." (PMID 32998690, 2020). "A subsequent bioinformatics analysis revealed cancer-associated somatic mutations, including KMT2B c.7804A > G DNA (protein: p.Ile2602Val) and MGA c.3628C > G DNA (protein: p.Arg1210Gly) with allele frequencies of 13.06% and 6.12%, respectively." (PMID 31882696, 2019). "In addition, MGA protein is considered an important protein for cancer development; however, studies on the function of this protein are lacking." (PMID 41154723, 2025). "MGA has been implicated in cancer, although its driver status is not confirmed, and occurs in a haploid state in nearly all DFT1s." (PMID 37079675, 2023). "Several loci show plausible evidence of positive selection in DFT1 or DFT2, including loss of chromosome Y and inactivation of MGA, but none are common to both cancers." (PMID 37079675, 2023). "As the parent gene of circMGA, MGA could negatively regulate cancer cell proliferation and act as an inhibitor for MYC target genes; here in myoblast cells, circMGA shared the same repression on proliferation." (PMID 35405864, 2022). "For instance, transcription factors MGA and KLF5 harbor mutations within their basic helix-loop-helix and C2H2-ZF domains, respectively, that alter their DNA base-binding positions, suggesting cancer-specific changes to normal DNA-binding and downstream regulatory activity." (PMID 32711844, 2020). "The other genes upregulated belonged mainly to the “cancer” and cell death functions (NFAT5, BMO2K, DLST, IL6ST, FAM76B, and MGA)." (PMID 22619672, 2012). "Interestingly, very recent studies showed that MGA, L3MBTL2 and PCGF6 are also destabilized upon USP7 inactivation in human cancer cell lines, indicating conserved USP7 function through mammalian evolution." (PMID 36772830, 2023).
MGA also shares sentences with these, for which no sentence is quoted: hematological neoplasms (3 papers); infection (3); bladder cancer (2); breast carcinoma (2); endometrial carcinoma (2); glioma (2); hematologic malignancies (2); ovarian carcinoma (2); acute lymphoblastic leukemia (1); adenocarcinoma (1); chronic lymphocytic leukemia (1); infectious disease (1); kidney carcinoma (1); mental retardation (1); metabolic disorder (1); neurological disorders (1); Premature ovarian insufficiency (1); prostate carcinoma (1); psoriasis (1); retinoblastoma (1); sarcoma (1); schizophrenia (1); seminoma (1); undifferentiated sarcoma (1); virus infection (1).